RHOA (ras homolog family member A)
Diseases named in the same sentence as RHOA in open-access papers (continued):
Sharing a sentence is not in itself a finding about the gene and the disease.
peripheral nerve injury (2 papers, 2012 to 2025). Injury to a peripheral nerve. "Additional findings implied that the loss of pain transmission through C-fibers is induced by the activation of the LPA1 receptor and its downstream RhoA/ROCK signaling pathway following peripheral nerve injury." (PMID 40249935, 2025).
pregnancy hypertension (2 papers, 2008 to 2021). "These research reveal that the Ca2+ sensitivity signaling pathway through RhoA/ROCK/MYPT1 contributes to pregnancy hypertension." (PMID 34357074, 2021). "These indicate that in the Ca2+ sensitization signaling pathway, not only the RhoA/ROCK/MYPT, but also the PKC/CPI-17 pathways are important in the regulation of vascular contraction in pregnancy hypertension." (PMID 34357074, 2021).
prion disease (2 papers, 2017 to 2020). A transmissible disease that is caused by a protein that is able to induce abnormal folding of normal cellular proteins, leading to characteristic spongiform brain changes, which are associated with neuronal loss without an inflammatory response. "Since neuronal loss is one of the major pathological changes in prion diseases, RhoA activation may participate in prion pathogenesis." (PMID 32070020, 2020). "Interestingly, our study also found that the interaction between RhoA and Cx43 was increased in models of prion disease." (PMID 32070020, 2020). "Consequently, these findings suggest that the regulation of RhoA activity via changes in its binding capacity with p190RhoGAP may play an important role in prion disease." (PMID 32070020, 2020). "However, the regulatory roles of Cx43- and RhoA/ROCK-related signaling molecules in prion diseases remain unknown." (PMID 32070020, 2020). "Here, we investigated the role of RhoA/ROCK signaling and Cx43 in prion diseases using in vitro and in vivo models." (PMID 32070020, 2020). "In conclusion, our results demonstrate that RhoA/ROCK activation, which enhances Cx43 hemichannel function, is involved in the pathogenesis of prion disease, leading to neuronal cell death." (PMID 32070020, 2020). "Therefore, the present study aimed to determine the regulatory role of the RhoA/ROCK and Cx43 signaling pathways in prion pathogenesis in both in vitro and in vivo models of prion disease." (PMID 32070020, 2020). "However, whether there is a link between RhoA/ROCK and Cx43 in prion disease pathogenesis is uncertain." (PMID 32070020, 2020). "In this study, we demonstrated a novel mechanism by which scrapie infection induced the activation of the RhoA/ROCK-Cx43 signaling pathway, which controls the accumulation of PrPSc and the functional properties of hemichannels and has an important role in the pathogenesis of prion diseases." (PMID 32070020, 2020).
progeria (2 papers, 2020 to 2023). "We propose that RhoA activation is an indirect outcome of the LMNA mutation in progeria cells through two possible mechanisms." (PMID 32710480, 2020). "We observed that increased cytoskeletal stiffness and RhoA activation in progeria cells were directly coupled with increased nuclear blebbing, Sun2 expression, and micronuclei‐induced cGAS‐Sting activation, part of the innate immune response." (PMID 32710480, 2020). "There is increased RhoA activation and cytoskeleton stiffness in progeria cells, which mediates increased nuclear blebbing, micronuclei formation, innate immune response, and cellular senescence." (PMID 32710480, 2020). "Our results reveal the mechanical mechanism of how RhoA/ROCK activation promotes cellular senescence by modulating F‐actin polymerization in progeria cells." (PMID 32710480, 2020). "Our results strongly suggest that increased cytoskeletal stiffness and RhoA activation in progeria cells are determinant for this disrupted adipo‐osteogenic balance of cell fate." (PMID 32710480, 2020). "Our results also demonstrate that there is sustained activation of RhoA signaling in progeria cells, which promotes F‐actin cytoskeletal stiffness and impairs proper F‐actin dynamics." (PMID 32710480, 2020). "Thus, inhibition of RhoA activation potentially rescues progeria phenotypes by relieving cytoskeletal stiffness and consequently nucleoskeletal stiffness." (PMID 32710480, 2020). "In addition, systemic inhibition of RhoA/ROCK signaling in progeria mice was able to rescue the progeria phenotypes in skeletal muscle." (PMID 32710480, 2020). "Based on the results above, we hypothesized that inhibition of RhoA signaling could suppress senescent phenotypes in progeria cells by reducing polymerized F‐actin and relaxing the cytoskeleton stiffness." (PMID 32710480, 2020). "RhoA activation in progeria cells could be a result of Sun2 activation as well as increased pro‐inflammatory signaling, pro‐fibrotic signaling, DNA damage, ROS production, and activated mechano‐sensing signaling." (PMID 32710480, 2020). "We have proposed the potential mechanisms of cytoskeletal stiffening in mediating nuclear blebbing, micronuclei formation, and cellular senescence, the involvement of the RhoA and Sun2 factors, and how increased ECM, nucleoskeletal, and cytoskeletal stiffness may be coupled in progeria cells." (PMID 32710480, 2020).
psoriasis (2 papers, 2015 to 2024). An autoimmune condition characterized by red, well-delineated plaques with silvery scales that are usually on the extensor surfaces and scalp. "Nevertheless, the results suggest that basally applied C3bot had only minor effects on the psoriasis-like phenotype despite inhibition of RhoA and reduction of IL-6 abundance in induced psoriasis." (PMID 37707681, 2024).
Rotavirus infection (2 papers, 2012 to 2018). Infection with any of the rotaviruses. "No phosphorylation of RhoA was observed in mock-infected control cells, thus suggesting that rotavirus infection results in the activation of the RhoA protein that induces the subsequent formation of actin stress fibers." (PMID 23082182, 2012). "The results indicate that rotavirus infection induces the activation of RhoA at early stages of infection." (PMID 23082182, 2012). "Moreover, we present evidence that rotavirus infection induces the activation of the small GTPase RhoA and the formation of stress fibers, which are independent of Ca2+ changes." (PMID 23082182, 2012). "Our data further demonstrated that the dissociation of TJs in MDCK cells, as a result of rotavirus infection or VP8* treatment, is due to the activation of the RhoA/ROCK/MLC signaling pathway." (PMID 30224682, 2018).
scrapie (2 papers, 2020 to 2022). A fatal disease of the nervous system in sheep and goats, characterized by pruritus, debility, and locomotor incoordination. "To confirm these results, we examined the effect of PrPSc on RhoA activity and the phosphorylation levels of RhoA downstream proteins in the brains of control and 22L scrapie-infected mice." (PMID 32070020, 2020). "The RhoA-p190RhoGAP interaction was significantly reduced in the brains of scrapie-infected mice compared to that in the brains of control mice." (PMID 32070020, 2020). "Moreover, RhoA and Cx43 colocalization was more visible in both the membrane and cytoplasm of scrapie-infected hippocampal neuronal cells than in controls." (PMID 32070020, 2020). "Furthermore, RhoA and Cx43 colocalization was more intensely detected in the membrane and cytoplasm in scrapie-infected cells than in control cells." (PMID 32070020, 2020). "Interestingly, Y27632 and Tat-C3 treatment significantly decreased PrPSc accumulation, Cx43 expression, and the interaction between RhoA and Cx43 in scrapie-infected hippocampal neuronal cells." (PMID 32070020, 2020). "Finally, RhoA and ROCK inhibition reduced PrPSc accumulation and the RhoA/Cx43 interaction, leading to decreased Cx43 hemichannel activity in scrapie-infected hippocampal neuronal cells." (PMID 32070020, 2020). "Therefore, we examined whether RhoA/ROCK inhibition modulates Cx43 hemichannel function in scrapie-infected hippocampal neuronal cells and found that RhoA/ROCK inhibition significantly decreased EtBr uptake and dye transfer in cells." (PMID 32070020, 2020). "Furthermore, we examined whether RhoA-mediated signaling is responsible for F-actin formation in control and 22L scrapie-infected cells." (PMID 32070020, 2020). "However, inhibition of RhoA and ROCK by treatments with Tat-C3 and Y27632 reduced F-actin formation and dynamics in scrapie-infected neural stem cells, suggesting that scrapie infection exerts its influence on cytoskeletal rearrangement through the modulation of RhoA and ROCK activity." (PMID 32070020, 2020). "As expected, we observed an increase in RhoA-GTP levels as well as a decrease in P-RhoA levels and increases in P-LIMK1/2 and P-cofilin levels in the brains of scrapie-infected mice compared to those of control mice." (PMID 32070020, 2020). "Interestingly, RhoA and ROCK inhibition decreased F-actin formation in scrapie-infected hippocampal neuronal cells." (PMID 32070020, 2020). "Thus, to elucidate whether RhoA/ROCK activity is involved in mitochondrial fission in 22L scrapie-infected CxN cells, cells were treated with either Y27632 (a ROCK inhibitor) or Tat-C3 (a specific inhibitor of RhoA) after scrapie infection." (PMID 36078152, 2022). "Therefore, we examined whether scrapie infection affects the interaction between RhoA and p190RhoGAP, which can regulate the RhoA/ROCK signaling pathway, by performing a coimmunoprecipitation assay using scrapie-infected hippocampal neuronal cells and the brains of control and scrapie-infected mice." (PMID 32070020, 2020).
Shock (2 papers, 2014 to 2015). The state in which profound and widespread reduction of effective tissue perfusion leads first to reversible, and then if prolonged, to irreversible cellular injury. "This was followed by a decline in RhoA levels after 2 h of hemorrhagic shock, that was accompanied by decreased CF and tone." (PMID 24710574, 2014).
spina bifida (2 papers, 2023). A congenital neural tube defect in which vertebrae are not fully formed. "In order to further unravel the molecular pathogenesis of spina bifida in the ZicKu model, it will be important to determine the pathways that link function of Zic2 with regulation of the critical BMP and RhoA signalling pathways that we have identified." (PMID 36916392, 2023). "Together, these results indicate that in the background of Vangl2Lp/+, the occurrence of spina bifida due to the heterozygosity of Cdh2 was not evoked by changes in the signal strength of the RhoA-Mypt1 or JNK-Jun pathways." (PMID 36890135, 2023).
synucleinopathies (2 papers, 2024). "Beyond known PD genes GBA1 and LRRK2, rare variants AD genes (CD33, CR1 and PSEN2) and Aβ toxicity modifiers involved in RhoA/actin cytoskeleton regulation (ARGHEF1, ARHGEF28, MICAL3, PASK, PKN2, PSEN2) were shared risk factors across synucleinopathies." (PMID 38496508, 2024). "Actin pathology occurred in iPSC synucleinopathy models and RhoA downregulation exacerbated ɑS pathology." (PMID 38496508, 2024).
testicular cancer (2 papers, 2017 to 2018). A primary or metastatic malignant neoplasm that affects the testis. "To date, the level of RhoA expression was proved to increase in skin, gastric, testicular cancer and so on." (PMID 28184030, 2017).
tuberous sclerosis (2 papers, 2021). Hereditary disease characterized by seizures, intellectual disability, developmental delay, and skin and ocular lesions. "Because tuberous sclerosis complexes also regulate RhoA-signalling, the inhibition also activates RhoA and increases basal (unstimulated) vascular permeability." (PMID 33718448, 2021).
adenoid cystic carcinoma (1 paper, 2021). A malignant tumor arising from the epithelial cells. "It has been demonstrated previously that substrate stiffness regulated migration and invasion ability of adenoid cystic carcinoma cells via the RhoA/ROCK pathway." (PMID 33415745, 2021).
adenovirus infection (1 paper, 2014). "We found that TCTP over-expression by adenovirus infection up-regulated RhoA pathway including the expression of RhoA, and its downstream signalings, phosphorylation of myosin phosphatase target protein (MYPT-1), and myosin light chain (MLC)." (PMID 24918292, 2014).
airway allergy (1 paper, 2022). "Our previous work showed that RhoA had the effects on inducing airway allergy in mice through promoting the oxidative stress in epithelial cells." (PMID 35910793, 2022). "In other words, the current study identified that RhoA was also a potential therapeutic target for airway allergy in addition to XBP1." (PMID 35910793, 2022). "The data suggest that XBP1 and RhoA are potential new targets for the treatment of airway allergy." (PMID 35910793, 2022). "The inhibition of either Etr or RhoA, or the depletion of XBP1 in CD4+ T cells, prevented the induction of airway allergy using the MNP.Derf1 protocol." (PMID 35910793, 2022). "Blocking XBP1 or RhoA can inhibit experimental airway allergy, suggesting that blocking RhoA or XBP1 has translation potential for treating airway allergy." (PMID 35910793, 2022).
amnestic disorder (1 paper, 2023). Systematic and extensive loss of memory caused by organic or psychological factors. "Additionally, neurodegenerative disease and amnestic disorder were among the disease alliance enriched terms and included MAP4 and RHOA proteins (FDR = 0.042)." (PMID 38107644, 2023).
ankylosing spondylitis (1 paper, 2022). An autoimmune chronic inflammatory disorder characterized by inflammation in the vertebral joints of the spine and sacroiliac joints. "However, Rac1 seems to be an important player concerning OPC migration, which could also be confirmed in a model of Ankylosing spondylitis (AS) and so we conclude that inhibition of RhoA released Rac1 from blockage by RhoA and therefore intensified the motility of OPCs." (PMID 36531963, 2022).
atopic dermatitis (1 paper, 2025). "Finally, the epidermis in a mouse atopic dermatitis model had increased active RhoA, phospho-GEF-H1 and phospho-KRD levels." (PMID 40746859, 2025).
autoimmune myocarditis (1 paper, 2024). Autoimmune myocarditis is an autoimmune disease that affects the heart. "The current results together with the previous ones indicate that simvastatin in the autoimmune myocarditis model affects not only MMP-9 activity but also the activity of the RhoA/ROCK pathway." (PMID 38540212, 2024). "As RhoA activation and RhoA-dependent downstream signaling play important roles in stress-exposed cardiomyocytes and the immune response, upregulation of the RhoA/ROCK pathway may be expected in autoimmune myocarditis." (PMID 38540212, 2024). "Another limitation is that induction of the RhoA/ROCK system has been demonstrated in a rat model of autoimmune myocarditis and not in humans." (PMID 38540212, 2024). "Our findings suggest that the RhoA/ROCK pathway is upregulated in EAM, and simvastatin in EAM settings inhibits the RhoA/ROCK pathway at the stage of phosphorylation of myosin light chains and provides a new insight into the molecular pathology of autoimmune myocarditis." (PMID 38540212, 2024). "They provide a new insight into the molecular pathology of autoimmune myocarditis and also make an important contribution to the study of the relationship between two important pathogenetic pathways resulting from the activation of MMP-9 and RhoA." (PMID 38540212, 2024). "Although many studies have proven the involvement of the RhoA/ROCK pathway in the development of autoimmune and cardiovascular diseases, its involvement in the pathomechanism of autoimmune myocarditis has not been investigated except for one publication on this subject." (PMID 38540212, 2024).
AV block (1 paper, 2024). "In chick embryos, utilising the Y27632 inhibitor caused AV block and established that RhoA-ROCK signalling was essential for the maintenance of the myocardial continuity between the sinus venosus and the atrioventricular node." (PMID 39435333, 2024).
basal cell carcinoma (1 paper, 2025). A carcinoma involving the basal cells. "Similarly, RhoA/ROCK is controlled by the TRPV4 channel and the activation of RhoA/ROCK has been shown to regulate downstream signaling transcription factors including Stat3 and Gli1 in amoeboid cancer cells and basal cell carcinomas, respectively." (PMID 40682198, 2025).
bone cancer (1 paper, 2025). A primary or metastatic malignant neoplasm affecting the bone or articular cartilage. "On the contrary, the knockdown of Slit2 increased the levels of Robo1 and RhoA, inhibited excitatory synaptogenesis, and alleviated bone cancer pain." (PMID 40249935, 2025). "Moreover, increased expression of p-RhoA and RhoA has been reported in the spinal cords of rats with bone cancer pain (BCP)." (PMID 40249935, 2025). "This research suggested that spinal RhoA/ROCK2 in neurons may be a key downstream target for CXCR4-mediated neuronal sensitization in bone cancer pain." (PMID 40249935, 2025). "Further research demonstrated that LPA augmented calcium influx prompted by α, β-meATP via P2X3R in primary DRG neurons from rats experiencing bone cancer pain, which could be blocked by the LPAR1 antagonist VPC32183 and the RhoA inhibitor C3 exoenzyme." (PMID 40249935, 2025).
Cachexia (1 paper, 2024). Severe weight loss, wasting of muscle, loss of appetite, and general debility related to a chronic disease. "Mechanistically, lactate/GPR81-induced cachexia occurs independently of the well-established protein kinase A catabolic pathway, but it is mediated by a signalling cascade sequentially activating Gi–Gβγ–RhoA/ROCK1–p38." (PMID 38499763, 2024).
celiac disease (1 paper, 2021). An autoimmune genetic disorder with an unknown pattern of inheritance that primarily affects the digestive tract. "In particular, a critical involvement of the RhoA/ROCK also in the epithelial barrier dysfunctions has been reported, affecting the apical junctional complex and thus epithelial barrier integrity, under adverse intestinal conditions (i.e., IBDs, celiac disease)." (PMID 34199160, 2021).
Cerebral Cavernous Malformation 2 (1 paper, 2019). "ERK2 is required for SCFFBXL19-mediated RhoA ubiquitination, while Cerebral Cavernous Malformation 2 (CCM2) has been demonstrated to act as an important scaffolding protein in facilitating Smurf1-mediated RhoA degradation." (PMID 31623230, 2019).
Chlamydia infection (1 paper, 2021). "InaC is required to activate both ARF1 and RhoA, which is tightly regulated during Chlamydia infection." (PMID 34903051, 2021). "To assess whether Chlamydia infection influences the activation state of RhoA to promote actin polymerization around the inclusion, we infected HeLa cells with C. trachomatis L2 and generated lysates from mid to late times postinfection (16 to 48 hpi)." (PMID 34903051, 2021). "Next, we assessed the kinetics of actin scaffold formation in the presence and absence of RhoA during Chlamydia infection." (PMID 34903051, 2021).
chorioamnionitis (1 paper, 2020). A morphologic finding indicating inflammation of the fetal sac membranes. "RhoA GTPase signaling pathways have been implicated in preterm births, but have, to our knowledge, not been studied in cord blood monocytes or in association with chorioamnionitis." (PMID 32612607, 2020).
cobblestone lissencephaly (1 paper, 2021). "Conditional deletion of RhoA (Ras homolog family member A) in neural progenitors leads to the disruption of apical anchoring and mis-orientation of aRG processes which results in heterotopia underneath a thinner cortex, reminiscent of cobblestone lissencephaly." (PMID 35069108, 2021).
Cocaine addiction (1 paper, 2025). "The results revealed RhoA/ROCK signaling pathway exhibited significant changes in several pathways that are closely related to neuroplasticity, such as Cocaine addiction, Sphingolipid metabolism, Ether lipid metabolism, Steroid hormone biosynthesis, Retinol metabolism and Phagosome." (PMID 40495884, 2025).